LPIN2 (lipin 2)
Description:
Acts as a magnesium-dependent phosphatidate phosphatase enzyme which catalyzes the conversion of phosphatidic acid to diacylglycerol during triglyceride, phosphatidylcholine and phosphatidylethanolamine biosynthesis in the endoplasmic reticulum membrane. Plays important roles in controlling the metabolism of fatty acids at different levels. Also acts as a nuclear transcriptional coactivator for PPARGC1A to modulate lipid metabolism.
Synonyms: KIAA0249; CRMO1; MJDS
Tractability: Antibody: the Human Protein Atlas places it where antibodies can reach. PROTAC: ubiquitination databases record sites on it; its protein half-life has been measured.
Gene: Protein-coding gene on chromosome 18 (2,885,296 to 3,013,345, reverse strand). Ensembl gene ENSG00000101577.
Subcellular location: Nucleus; Cytoplasm, cytosol; Endoplasmic reticulum membrane
Subcellular location (Human Protein Atlas): Cytosol; Actin filaments; Plasma membrane
Pathways (Reactome):
Metabolism: Synthesis of PC; Synthesis of PE; Triglyceride biosynthesis
Cell Cycle: Depolymerization of the Nuclear Lamina
Gene Ontology:
Molecular function: phosphatidate phosphatase activity; transcription coactivator activity
Biological process: cellular response to insulin stimulus; fatty acid catabolic process; lipid metabolic process; positive regulation of transcription by RNA polymerase II; triglyceride biosynthetic process
Cellular component: cytosol; endoplasmic reticulum membrane; nucleus
Genetic constraint (gnomAD): Loss-of-function variants: 45 observed, 99.21 expected, observed/expected ratio (o/e) 0.45, 90% interval 0.36 to 0.58. The upper end of that interval is the gene's LOEUF score, 0.58, which puts it in group 2 of 6, group 1 being the genes least tolerant of losing a copy. Missense variants: 891 observed, 1,061.3 expected, observed/expected ratio (o/e) 0.84, 90% interval 0.79 to 0.89. Synonymous variants: 399 observed, 405.29 expected, observed/expected ratio (o/e) 0.98, 90% interval 0.91 to 1.07.
Gene-disease validity (ClinGen):
ClinGen rates the evidence that LPIN2 causes each of these diseases.
Majeed syndrome (autosomal recessive): Definitive. Majeed syndrome is a rare genetic multisystemic disorder characterized by the triad of chronic recurrent multifocal osteomyelitis, congenital dyserythropoietic anemia, and variable transient inflammatory dermatosis.
Homologues: Orthologues: chimpanzee LPIN2 (99% identical), macaque LPIN2 (99% identical), rabbit LPIN2 (94% identical), dog LPIN2 (93% identical), rat Lpin2 (90% identical), mouse Lpin2 (90% identical), pig LPIN2 (90% identical), guinea pig LPIN2 (84% identical), tropical clawed frog lpin2 (72% identical), zebrafish lpin2 (66% identical), Drosophila melanogaster Lpin (37% identical), Caenorhabditis elegans lpin-1 (28% identical). Paralogues in human: LPIN1 (51% identical), LPIN3 (48% identical), AP5Z1 (13% identical).
Diseases named in the same sentence as LPIN2 in open-access papers:
LPIN2 is named in the same sentence as 46 diseases in open-access papers, as found by Europe PMC text mining. Sharing a sentence is not in itself a finding about the gene and the disease. The quoted sentences say what the papers report.
Majeed syndrome (27 papers, 2010 to 2025). "Majeed syndrome, seen in people with lipin-2 inactivating point mutations, is a painful inflammatory disorder, episodes of which cause anemia, fever, and pain in bones and joints." (PMID 41109341, 2025). "Recessive loss-of-function mutations in LPIN2 are involved in the dysregulation of innate immune responses resulting in systemic inflammation and osteomyelitis, including Majeed syndrome." (PMID 37273692, 2023). "A loss of function mutation in LPIN2 has been found in affected individuals with Majeed Syndrome, another rare monogenic form of CNO." (PMID 37342528, 2023). "Lpin2 encodes Lipin-2, a protein likely involved in lipid metabolism, and has been found to be polymorphic in autosomal disease myopia and Majeed syndrome, a human inflammatory disorder." (PMID 36278681, 2022). "It is noteworthy that human CDA patients with Majeed syndrome caused by LPIN2 variants have a hypochromic microcytic anemia with dyserythropoeisis, but also chronic recurrent multifocal osteomyelitis and inflammatory dermatosis." (PMID 36140701, 2022). "Lpin2 alterations cause Majeed syndrome, which is characterized by chronic autoinflammatory multifocal osteomyelitis." (PMID 33809261, 2021). "Alterations in human Lpin2 cause Majeed syndrome, a rare inherited autosomal recessive autoinflammatory bone disorder that is characterized by early onset chronic multifocal osteomyelitis, neutrophilic skin inflammation, and dyserythropoietic anemia." (PMID 33809261, 2021). "Monogenic Lpin2 mutation causes familial chronic multifocal osteomyelitis and osteolytic foci that are characteristic of Majeed syndrome." (PMID 33809261, 2021). "Homozygous mutations in LPIN2 result in the autoinflammatory disease Majeed syndrome, characterized by chronic recurrent multifocal osteomyelitis, skin inflammation, and dyserythropoietic anemia." (PMID 33869291, 2021). "While a direct connection to IL-1 signaling is evident in DIRA, that connection had been less clear in the Majeed syndrome which is caused by pathogenic variants in LPIN2, in which the encoded protein plays a central role in lipid metabolism." (PMID 33670882, 2021). "Five of the 9 LPIN2 mutations identified in affected individuals with Majeed syndrome are predicted to cause an early termination codon and a truncated protein, if the mRNA escapes the nonsense-mediated RNA decay and one is a whole gene deletion." (PMID 33670882, 2021). "The last disease in this section is Majeed syndrome, which is an autosomal recessive disorder due to mutations in LPIN2 that encodes the protein LIPIN2, a negative regulator of NLRP3 inflammasome." (PMID 33042144, 2020). "In Majeed syndrome, an autosomal recessive inheritance has been documented with mutations in the lipin-2 gene (LPIN2)." (PMID 32705386, 2020). "The importance of lipin 2 in human physiology is also demonstrated by the observation that mutations in lipin 2 cause Majeed’s syndrome, an inflammatory syndrome of osteomyelitis; the mechanistic basis for which is poorly understood." (PMID 33003344, 2020). "Mutations in the LPIN2 gene, located on the short arm of chromosome 18, have been identified as being responsible for Majeed syndrome." (PMID 31727123, 2019). "IL-1 blockade results in dramatic improvement in clinical and laboratory parameters of inflammation in Majeed syndrome, confirming that loss of LPIN2 in these patients leads to autoinflammation via enhanced IL-1β production." (PMID 30766537, 2019). "A diagnosis of Majeed syndrome was confirmed for patient 29 with a very typical phenotype and compound heterozygous mutations in LPIN2 (p.P626S and p.S203F)." (PMID 28750028, 2017). "Majeed syndrome follows an autosomal-recessive inheritance and has been linked with mutations in the LPIN2 gene, encoding for the Lipin2 protein." (PMID 24359092, 2013). "In humans and mice, Lpin-1 is associated with metabolic syndrome and type 2 diabetes and mutations in human LPIN2 cause Majeed syndrome." (PMID 23496871, 2013).
Majeed syndrome (continued). "There is an autosomal recessive syndromic form of CRMO (Majeed syndrome) which is caused by mutations in LPIN2." (PMID 20955551, 2010). "In addition, the R736H/C (R193 in Tt Pah2) mutations have been reported in patients with lipin-2 loss-of-function causing Majeed syndrome." (PMID 41109341, 2025). "Majeed syndrome is an autoinflammatory disorder that manifests as chronic multifocal osteomyelitis, neutrophilic cutaneous inflammation, and dyserythropoietic anemia, which is caused by LPIN2 mutation." (PMID 37964368, 2023). "Interestingly, mono-allelic LPIN2 variants in family members of Majeed syndrome patients associate with an increased risk for psoriasis." (PMID 33869291, 2021). "LPIN2 loss of function in humans leads to Majeed Syndrome, a rare, recessively inherited disorder that is characterized by the triad of early-onset chronic recurrent multifocal osteomyelitis (CRMO), dyserythropoietic anemia (typically microcytic), and neutrophilic skin lesions." (PMID 30766537, 2019). "The S734L mutation in lipin 2 (motif II), which eliminates PAP activity, causes Majeed syndrome, an inflammatory disorder characterized by recurrent osteomyelitis, fever, dyserythropoietic anemia, and skin inflammation." (PMID 40680843, 2025). "Majeed syndrome is an autosomal recessive autoinflammatory disease caused by mutations in LPIN2, which encodes for Lipin-2." (PMID 39618694, 2024). "In studies of Majeed syndrome, lipin 2 was found to be expressed in numerous tissues —most prominently in the liver, followed by kidney, lung, gut, and brain." (PMID 37964368, 2023). "There are also key differences in the phenotypes seen in Majeed syndrome and that seen in Lpin2 knockout mice." (PMID 33670882, 2021). "However, certain syndromic forms of CNO, like Majeed syndrome and deficiency of the IL-1 receptor antagonist (DIRA), have been linked to specific gene mutations (LPIN2 and IL1RN), shedding light on the role of IL-1β in inflammation." (PMID 38137947, 2023). "While the link between lipin-2 and inflammasome regulation has been established, further research is needed to understand the preferential target on bone that produces the clinical phenotype in Majeed Syndrome." (PMID 37342528, 2023). "Different data show that genetic metabolism errors are responsible for some of CRMO syndromes, for example, the PSTPIP1 gene is associated with pyogenic arthritis, pyoderma gangrenosum and acne (PAPA) syndrome as well as defects in LPIN2 result in Majeed syndrome." (PMID 30053822, 2018). "Majeed syndrome is a rare autosomal recessive clinical entity, first identified in 1989, caused by mutations in the LPIN2 gene, localized on the short arm of chromosome 18, which codifies the lipin-2 protein, expressed in liver, kidney, gastrointestinal tract, lymphatic tissue, and bone marrow." (PMID 25132737, 2014). "Because of the dyserythropoesis in Majeed syndrome, it has been proposed that LPIN2 could also play a role in mitosis, and that an impaired function may lead to abnormal mitosis in rapidly dividing cells, including the red blood cell lineage in the bone marrow." (PMID 22685464, 2012). "Recently, lipin-2 has been reported to regulate P2X7 receptor sensitization to limit overactivation of NLRP3 inflammasome, which may provide clues to better understand the molecular features that characterize the high IL-1β production found in Majeed syndrome patients with LPIN2 mutations." (PMID 29255148, 2017).
osteomyelitis (6 papers, 2020 to 2025). An acute or chronic inflammation of the bone and its structures due to infection with pyogenic bacteria. "However, one limitation is that Lpin2 knockout mice lack phenotypes resembling osteomyelitis." (PMID 33809261, 2021).
diabetes (5 papers, 2015 to 2022). "Interestingly, polymorphisms in the LPIN1 and LPIN2 genes are associated with traits of metabolic disease, including insulin sensitivity, diabetes and increased blood pressure, as well as the response to thiazolidinediones." (PMID 26232096, 2015). "Lipin 2 mRNA is also induced in liver by fasting and diabetes, but lipin 1 and lipin 2 are under the control of different regulatory pathways." (PMID 33003344, 2020). "Although lipin 2 is more abundant than lipin 1 in normal mouse liver, hepatic lipin 1 expression is highly induced by fasting, diabetes, glucocorticoid administration, and experimental alcoholic fatty liver disease." (PMID 33003344, 2020). "In total, of the top five association signals that were mapped to genes (n = 103) we found five (CDKAL1, DCDC2C, KLF12, LPIN2, TLE1) to be related with diabetes." (PMID 31818369, 2019). "The increased expression of lipin-1 together with the fatty acid-induced translocation of lipin-1 and lipin-2 to the ER facilitates increased TAG synthesis in starvation, diabetes, and stress conditions." (PMID 30934807, 2019).
chronic recurrent multifocal osteomyelitis (4 papers, 2019 to 2021). "LPIN2 mutation causes Majeed syndrome, characterized by chronic recurrent multifocal osteomyelitis (CRMO)." (PMID 34262554, 2021). "Similarly, an intronic LPIN2 pathogenic variant (rs80338808) reported in a patient with chronic recurrent multifocal osteomyelitis (CRMO) and congenital dyserythropoietic anemia (CDA) caused a frameshift in exon 17 which resulted in early stop codon." (PMID 34177904, 2021).
myopia (3 papers, 2011 to 2023). "LPIN2 mutations link to increased IL-1β and activated NLRP3 inflammasome and may be related to myopia." (PMID 37965330, 2023).
Obesity (3 papers, 2010 to 2025). Accumulation of substantial excess body fat. "Lipin-2 is prominently expressed in the liver, and its hepatic expression is induced in mice by fasting and diet-induced obesity." (PMID 26086818, 2015). "Furthermore, calorie restriction and obesity have drastic opposing effects on pro- and anti-inflammatory genes as well as genes involved in adipose tissue energy metabolism such as Lpin2, Kcnj11 and Rbp4." (PMID 20307313, 2010). "We show that the CR increased the expression levels of anti-inflammatory genes Il-10 and Adrbk1 and energy homeostasis-related genes such as Ptgds, Lpin2, Angptl6, Kcnj11, and Dusp9 but were not affected by obesity in HF mice." (PMID 20307313, 2010).
type 2 diabetes (3 papers, 2013 to 2025). "LPIN2 played a significant part in regulating fatty acid metabolism at various levels that were associated with type 2 diabetes and fat distribution." (PMID 37165455, 2023).
Insulin resistance (2 papers, 2015 to 2020). Increased resistance towards insulin, that is, diminished effectiveness of insulin in reducing blood glucose levels. "Similarly, activation of lipin 2 in fatty liver or by ER stress was also shown to cause insulin resistance by this mechanism." (PMID 33003344, 2020). "Thus, a reduced Lpin2 expression in the liver of B6-Tg(Zfp69) mice might affect lipid metabolism leading to insulin resistance." (PMID 26232096, 2015).
melanoma (2 papers, 2014 to 2018). A malignant, usually aggressive tumor composed of atypical, neoplastic melanocytes. "We next investigated the functional significance of the association between SPRY4-IT1 and lipin 2 in melanoma cells using gene-specific RNAi." (PMID 25344859, 2014). "To investigate its function further, we affinity purified SPRY4-IT1 from melanoma cells and used mass spectrometry to identify the protein lipin 2, an enzyme that converts phosphatidate to diacylglycerol (DAG), as a major binding partner." (PMID 25344859, 2014). "We postulate that lipin 2 levels must be maintained on a steady state level in melanoma cells, and modulating lipin 2 levels (either an increase or decrease) can negatively affect cell physiology." (PMID 25344859, 2014). "It would be of interest to determine whether the influence of SPRY4-IT1 on melanocyte and melanoma proliferation involves inhibition of lipin 2 activity and/or activation of mTOR." (PMID 25344859, 2014). "To investigate the effect of SPRY4-IT1 modulation of lipin 2 expression on global lipid metabolism in melanoma cells, we subjected SPRY4-IT1 knockdown and control A375 cells to shotgun lipidomics, an MS-based assay that permits the quantification of changes in the cellular lipid profile." (PMID 25344859, 2014). "SPRY4-IT1, an lncRNA overexpressed in melanoma cells, negatively regulates triacylglycerol levels in melanoma cells and knockdown of SPRY4-IT1 can induce apoptosis via lipin 2-mediated alterations in lipid metabolism leading to cellular lipotoxicity." (PMID 30135656, 2018). "We showed that knockdown of SPRY4-IT1 modulates cellular concentrations of lipin 2 substrates, including phosphatidate, and cells expressing high SPRY4-IT1 levels, such as melanomas, might thus be expected to accumulate lipin 2 substrates." (PMID 25344859, 2014).
pyoderma gangrenosum (2 papers, 2018 to 2020). An idiopathic, rapidly evolving, and severely debilitating disease occurring most commonly in association with chronic ulcerative colitis. "Mutations involving different autoinflammatory genes (MEFV, NLRP3, NLRP12, NOD2, LPIN2, and PSTPIP1) have been reported in syndromic HS [pyoderma gangrenosum, acne, and hidradenitis suppurativa (PASH) syndrome] as well as in pyoderma gangrenosum (PG), a prototypic neutrophilic dermatosis." (PMID 32425927, 2020).
asthma (1 paper, 2024). "Single gene GSEA analysis revealed that HORMAD2, WNT10A, ATP6V1E2, CMBL, ARRDC4, and LPIN2 were primarily involved in Allograft rejection, Arginine biosynthesis, Asthma, and Fatty acid biosynthesis." (PMID 40635857, 2024).
Ataxia (1 paper, 2024). Ataxia refers to impaired coordination of voluntary muscle movement. "Lipin-2, with concomitant reduction of lipin-1 with age, can cause ataxia in Lipin-2 knockout mice." (PMID 38502583, 2024).
cervical cancer (1 paper, 2021). A primary or metastatic malignant neoplasm involving the cervix. "Then, we constructed a risk score model based on LPIN2, TEKT2, CXCL2, and FABP4, which had high accuracy in predicting the prognosis of cervical cancer patients." (PMID 34789197, 2021). "Another protective factor in cervical cancer found in the current study was LPIN2." (PMID 34789197, 2021). "Thus, LPIN2 may affect the prognosis of patients with cervical cancer via IL-1β." (PMID 34789197, 2021).
colorectal carcinoma (1 paper, 2014). A malignant epithelial neoplasm that arises from the colon or rectum and invades through the muscularis mucosa into the submucosa. "Indeed, increased levels of phosphatidate have been linked to certain types of cancers through allosteric activation of the molecular target of rapamycin (mTOR) and to a possible role for lipin 2 in statin resistance of colorectal carcinoma cells in vitro." (PMID 25344859, 2014).
diabetic encephalopathy (1 paper, 2023). A brain disease that is characterized by functional impairment of cognition, cerebral signal conduction, neurotransmission and synaptic plasticity, and underlying structural pathology associated with diabetes. "There was evidence supporting the anti-inflammatory properties of lipin 2 in immune cells in a recent study where lipin 2 protected against microglial NLRP3 inflammasome-mediated neuroinflammatory responses in diabetic encephalopathy in mice by inhibiting JNK and ERK pathways." (PMID 37964368, 2023).
glaucoma (1 paper, 2020). Increased pressure in the eyeball due to obstruction of the outflow of aqueous humor. "The enzymes depicted in red are upregulated in glaucoma, for example LPIN2 and PLPP3, whereas the GPAT4 depicted in blue are downregulated." (PMID 32602905, 2020).
heart failure (1 paper, 2021). Inability of the heart to pump blood at an adequate rate to meet tissue metabolic requirements. "The protein abundance of lipin 1 and expression of LPIN1 and LPIN2 mRNA were quantified in heart samples from humans with heart failure, obtained at the time of left ventricular assist device (LVAD) implantation." (PMID 33986192, 2021).
hepatoma (1 paper, 2011). "When human hepatoma cell line HepG2 cells were treated with taurocholic acid (TCA), the lipin-2 protein level decreased, while the lipin-1 protein was not changed under the same conditions." (PMID 21857965, 2011).
liver diseases (1 paper, 2025). "Silymarin/silybin regulates a significant number of these lipid metabolic genes, including iPLA2/PLA2G6, ATGL/PNPLA2, PLD1, LPIN2, and by trend PNPLA3 (which is a major genetic risk factor for MAFLD 131) and HSD17B13, counteracting the observed dysregulation in liver diseases." (PMID 39897559, 2025).
Mediterranean fever (1 paper, 2019). "Investigation of 7 cases of PASH and 13 cases of isolated PG revealed multiple mutations in a variety of autoinflammatory genes, including PSTPIP1, Mediterranean fever (MEFV), Nucleotide-binding oligomerization domain-containing protein 2 (NOD2), NLRP3, NLRP12, Lipin 2 (LPIN2)." (PMID 31139187, 2019).